COL1A1 (collagen type I alpha 1 chain)
Diseases named in the same sentence as COL1A1 in open-access papers (continued):
Sharing a sentence is not in itself a finding about the gene and the disease.
steatosis (continued). "Mice presented steatosis with an NAS score of 3 and fibrosis with a score of 1–3 and increased expression of fibrillary collagens such as col1a1 and collagen type 1 α 2 chain (col1a2)." (PMID 33324348, 2020). "The expression profiles of profibrotic genes such as CYGB, ACTA2, PCDH7, DES, COL1A1, and COL1A3 were also significantly up‐regulated in the co‐culture NASH model, when compared with the steatosis model." (PMID 31909357, 2020). "In contrast to many other dietary NASH models, this WD was also able to produce steatosis-induced fibrosis as shown by Sirius Red staining and hydroxyproline assay, α-SMA expression, and Col1A1 transcription products." (PMID 30949049, 2019). "Furthermore, the expression of the fibrosis-related genes Col1a1, Tgfb1, and Timp1 was lower in the HY7207 group than in the ND group These data imply that HY7207 ameliorates hepatic lipid accumulation, steatosis, inflammation, and fibrosis in mice with NAFLD." (PMID 39337360, 2024). "Histological examination using H&E, α-SMA, Masson, COL1A1 and FASN staining revealed that the degree of hepatic steatosis and hepatocellular ballooning in linc00907 knockdown mice was less severe than that in the control group, and lipid accumulation was also less pronounced." (PMID 38613803, 2024). "Interestingly, PDE4D level was not changed in patients with obesity, steatosis, or steatohepatitis or in obese (ob/ob) mice but was increased in the human cirrhotic liver and correlated with the levels of COL1A1 mRNA." (PMID 41196648, 2025).
Obesity (27 papers, 2010 to 2026). Accumulation of substantial excess body fat. "Given the strong link between obesity and T2D, it is possible that the COL1A1 rs1107946 variant influences metabolic pathways that predispose individuals to both conditions." (PMID 40507792, 2025). "For instance, the identification of FTO or PPARG risk alleles could guide early lifestyle interventions in individuals at high risk for obesity or type 2 diabetes, while variants in COL1A1 or IL6 may allow the identification of increased susceptibility to tendon or ligament injuries." (PMID 41300761, 2025). "Beyond their role in skeletal health, polymorphisms in the COL1A1 and COL1A2 genes have been implicated in the development of metabolic disorders such as obesity, type 2 diabetes mellitus (T2D), and cardiovascular disease." (PMID 40507792, 2025). "The pioneering findings related to COL1A2 rs42524 and maternal fracture history, COL1A1 rs1107946 and obesity/T2D, and the age-dependent effects of COL1A1 rs1800012 on BMD underscore the importance of genetic factors in bone and metabolic health." (PMID 40507792, 2025). "The COL1A1 rs1107946 AA genotype was associated with higher femoral neck BMD (p < 0.05), an over 10-fold increased obesity prevalence (p = 0.038), and a 3.5-fold higher T2D risk (p = 0.011)—a novel finding." (PMID 40507792, 2025). "This study analyzed the associations of COL1A1 (rs1107946, rs1800012) and COL1A2 (rs42524) polymorphisms with BMD, obesity, and type 2 diabetes (T2D) in 554 postmenopausal women." (PMID 40507792, 2025). "Obesity participates in cardiac fibrosis by up-regulating the expression of COL1A1 and COL1A2 in cardiac fibroblasts and further significantly increasing myocardial collagen content." (PMID 36547458, 2022). "We found a strong relationship between the COL1A1 rs1107946 AA genotype and obesity." (PMID 40507792, 2025). "Interestingly, ASPC3 was uniquely enriched for COL1A1, COL6A1, FN1, LOX, and LUM, which are fibrosis markers recently associated with a specific subset of PDGFRA+ progenitor cells in murine model of obesity." (PMID 36313560, 2022). "Obesity robustly induced transcription of fibrotic genes in both subcutaneous white AT (scWAT) and visceral white AT (vWAT), including Col1a1, Col6a1, and Mmp2, consistent with RNAseq analysis of adipocytes that acquire a fibroblast-like transcriptional signature in response to a HFD feeding." (PMID 36229481, 2022). "Even after fibrotic stimuli (e.g., alcohol, obesity) are removed, HSCs retain a fibrotic phenotype due to persistent histone H3K4 methylation at the COL1A1 promoter." (PMID 40149485, 2025). "Dysregulation of COL1A1 expression leads to ECM stiffness, impaired adipogenesis, and disrupted lipid metabolism, contributing to metabolic diseases such as obesity and insulin resistance." (PMID 40522964, 2025). "We observed significant upregulation of proteins like COL1A1, COL6A3, FABP4, and LEP in individuals with obesity, indicating potential roles in adipose tissue dysfunction and metabolic dysregulation." (PMID 38732002, 2024). "This analysis showed that some proteins, such as COL1A1, COL6A3, FABP4, LEP, LGALS1, and THBS4, are obesity-specific, and GDF15, LPL, MCFD2, REG1A, REG1B, and TCN2 are T2D-specific." (PMID 38732002, 2024). "Consistent with findings from the early-stages of diet-induced obesity studies, our network analysis identified increased expression of common collagen-related ECM transcripts COL1A1, COL3A1, COL16A1, COL4A4, and COL6A3." (PMID 26678390, 2015). "Additionally, COL1A1 and COL1A2 have been identified as hub genes in obesity-induced cardiac fibrosis." (PMID 37662841, 2023). "Moreover, we also performed qPCR on the eight most significantly up-regulated homeobox transcription factors, in addition to COL1A1 (most up-regulated gene) and COL6A3 (recently connected with obesity)." (PMID 20543949, 2010).
Obesity (continued). "Studying obesity with and without OSA, changes (unadjusted for multiple comparisons) in some peptides belonging to CDH13, FGB, COL1A1, and COL3A1 were also identified." (PMID 39858454, 2025).
pancreatic cancer (27 papers, 2015 to 2025). "These are very promising findings: whereas ZNF750 is a lineage-specific tumor suppressor in squamous cell carcinoma, COL1A1 is associated with many tumor entities including oral and pancreatic cancer with prognostic relevance." (PMID 37455825, 2023). "The gene expression analysis of EMT markers Zeb1, Vimentin, and Col1a1 were significantly decreased in YFP sorted primary pancreatic cancer cell lines from KPC;ST mice, along with complete loss of Snai1 and Twist1." (PMID 33852841, 2021). "Consistent with the observed PanIN lesions in the STP mice, overexpression of Ctgf and Col1a1, two biomarkers associated with desmoplasia in human pancreatic cancer were also upregulated in the STP mice relative to the MT-TGFα mice." (PMID 25803032, 2015). "As COL1A1 has been well studied in pancreatic cancer, we selected PLAU and CTSK, which have shown reductions in overall and disease-free survival." (PMID 38077303, 2023). "Suppression of fibrosis through deletion of Col1a1 from α-SMA+ myofibroblasts has also been recently shown to accelerate pancreatic tumor growth." (PMID 35081338, 2022). "Previous studies have shown that COL1A1 can participate in glutamine-mediated interaction between pancreatic cancer and stellate cells, and silencing COL1A1(siCOLIA1) inhibited the orthotopic growth of colorectal tumor in mice." (PMID 33850663, 2021). "Similarly, in pancreatic cancer, higher expression of COL1A1 has been found to enhance tumor cell proliferation and migration." (PMID 38913913, 2024). "Importantly, collagen I produced by CAFs is built up as heterotrimers (encoded by COL1A1 and COL1A2), whereas pancreatic cancer cells produce COL1A1 homotrimers due to promoter hypermethylation of the COL1A2 gene." (PMID 37174079, 2023). "The COL1A1 gene had a significantly higher expression in pancreatic cancer cells." (PMID 36415513, 2022). "However, the implication of dysregulated splicing pattern of COL1A1 in cancer, including pancreatic cancer with abundance fibrosis, remains to be elucidated." (PMID 31552163, 2019). "On the other hand, elevated mRNA levels of both COL1A1 and COL1A2 have been documented in colorectal, liver, ovarian, and pancreatic cancers, as well as in medulloblastoma." (PMID 41463322, 2025). "The results showed that COL1A1, PLAU, and CTSK were highly expressed in the three datasets, with COL1A1 having been shown to play a significant role in pancreatic cancer." (PMID 38077303, 2023). "COL1A1, COL1A2, ACTA2, PDGFRB and FAP displayed a significant positive correlation with this gene dataset in melanoma tumours (SKCM), whereas in pancreatic tumours (PAAD), that correlation was even stronger owing to their highly desmoplastic TME." (PMID 35654839, 2022). "We surveyed the coexpressed genes in the pancreatic cancer TCGA dataset and found that BMP1 was coexpressed with a large number of matrisome genes and especially collagen-related genes, such as COL1A1 and COL1A2." (PMID 33879793, 2021). "This was confirmed by the upregulated expression of desmoplasia-associated Col1A1 and chronic pancreatitis-related Muc6 detected in the STP mice, indicating that STP mice may be a suitable animal model for studying the transition of chronic pancreatitis to pancreatic cancer." (PMID 25803032, 2015). "Palmatine induced apoptosis by suppressing survivin and glioma-associated oncogene homolog (GLI) signaling pathways, as well as the activation of collagen type I alpha 1 (COL1A1), thereby disrupting glutamine-mediated crosstalk between pancreatic cancer cells (PCCs) and PSCs." (PMID 40786032, 2025). "Besides, the mRNA expression of FERMT2 positively correlated with ACTA2, COL1A1, FAP, and FSP based on TCGA pancreatic cancer data." (PMID 38910148, 2024).
pancreatic cancer (continued). "In agreement with previous reports on pancreatic cancer exosomes, we observed that UM-derived exosomes triggered the transactivation of HHSCs, which produced α-SMA and increased amounts of extracellular matrix (ECM) proteins such as FN1, FN-EDA, and Col1A1 as compared with controls." (PMID 39272836, 2024). "The other proteins in these pathways were members of the families of interleukin (ITGA2, ITGB6), laminin (LAMC2), and collagen (COL1A1/2, COL6A3), together with cartilage oligomeric matrix protein (COMP), whose role in pancreatic cancer has not yet been clarified." (PMID 33194391, 2020).
prostate carcinoma (24 papers, 2007 to 2026). A carcinoma that arises from epithelial cells of the prostate gland. "Increased expression of Col1A1 is present in cancer tissues and associated with increased tissue modulus as measured by ultrasound shear wave elastography in prostate cancer." (PMID 34771715, 2021). "Prostate cancer bone pathology is shaped by PCa exosomal miR-92a-1-5p, which suppresses COL1A1 to favor osteoclastogenesis, revealing a tractable EV-miRNA target in metastasis." (PMID 41304838, 2025). "Mechanistically, miRNA-92a-1-5p in prostate cancer-derived exosomes targets COL1A1 to promote osteoclast differentiation and inhibit osteoblast differentiation, thereby promoting bone metastasis of prostate cancer." (PMID 41430724, 2025). "Exosome cargo also reveals actionable biology—prostate cancer–derived exosomes transfer miR-92a-1-5p to suppress COL1A1, tipping bone homeostasis toward osteoclastogenesis and suggesting antimiR or EV-interception strategies against skeletal metastasis." (PMID 41304838, 2025). "To shed some light on the lower deposition of collagen type I, we analyzed COL1A1 production by human fibroblasts isolated from surgically resected normal and prostate cancer specimens (Fig. EV5F)." (PMID 38316991, 2024). "Differences in collagen content, orientation, distribution, structures, and type play a critical role in prostate cancer progression, demonstrating, by gene expression, that the amount of COL1A1 increased in cancer tissue compared to COL3A1." (PMID 37894275, 2023). "COL1A1 is also known as a key factor in predicting the prognosis and progression of prostate cancer." (PMID 36010952, 2022). "The means of the gene expression level of COL1A1 in prostate cancer tissue in GS 3 + 3, 3 + 4, 4 + 3, 3 + 5, and 4 + 5 were 383, 920.6, 2729, and 927, respectively, while in COL3A1 they were 48.6, 114.2, 198.5, and 163.7, respectively." (PMID 34771715, 2021). "COL1A1 expression has been found to promote prostate cancer progression." (PMID 38441550, 2024). "Moreover, we found that both SPARC and COL1A1 harbor SNVs and CNVs in TCGA prostate cancer samples and their expressions were obviously correlated to the survival of patients." (PMID 34131148, 2021). "However, by using logistic regression strategy, we found and validated that several VUS-containing genes (COL1A1, CSF3R, ERBB2, ITGB8, TSC1 and TSC2) in the PI3K-Akt signaling pathway can improve the predicting of metastasis in prostate cancer patients in Hong Kong and Shanghai cohorts." (PMID 36095024, 2022). "In summary, COL1A1 may be a negative prognostic factor for prostate cancer." (PMID 40093812, 2025).
diabetes (23 papers, 2013 to 2025). "The UCD‐T2DM rat has a polygenic origin of diabetes and may be susceptible to fibrosis early in its lifespan; thus, the decrease Col1a1 and Col3a1 in an advanced state of diabetes could be a compensation mechanism for excess colonic fibrosis in this model." (PMID 34806320, 2021). "Our data indicate a consistent decline in COL1A1 expression levels in diabetic mice, correlated with elevated glucose levels and the progression of diabetes." (PMID 39296334, 2024). "The chi‐square test and correlation analysis demonstrated that the relative expression levels of keratin 17 (KRT17) and collagen type I α1 chain (COL1A1) were significantly higher in EC with diabetes." (PMID 38979664, 2024). "All these suggest that targeted screening for COL1A1 expression should be focused on individuals of younger age (<66 years), and at the same time, those esophageal tumor patients with hyperglycemia or diabetes should be strengthened for COL1A1 gene screening." (PMID 38979664, 2024). "Relative expression of KRT17 and COL1A1 was both higher in ESCC patients with diabetes and correlated with blood glucose levels." (PMID 38979664, 2024). "Gene expression of the myofibroblast marker α-smooth muscle actin (Acta2) and matrix molecules collagen 1 (Col1a1), collagen IV (Col4a3) and fibronectin (Fn1) were all increased 2- to 3- fold in kidneys at week 12 of diabetes." (PMID 38391050, 2024). "In this study, TERT and COL1A1 were utilized as markers to evaluate the implications of diabetes on aging." (PMID 39296334, 2024). "On day 28 post-fracture, our 2-way ANOVA evidenced a significant main effect of diabetes on Col1a1 (p=0.0002), Runx2 (p=0.0008), and Osx (p=0.01) expression when comparing diabetic and non-diabetic rats." (PMID 36060973, 2022). "Still, two transcripts related to collagen synthesis (Col1a1 and Col3a1) were reduced in D3M rats compared to ND rats, suggesting that the advancement of diabetes weakens the structural strength and integrity of the colon." (PMID 34806320, 2021). "The advancement of diabetes was synchronized with COL1A1 hypermethylation." (PMID 39296334, 2024). "In fact, in this study we also demonstrated that a downregulation of LEF-1 in T2D bone goes along with a downregulation of COL1A1, strengthen data of a reduced production of bone matrix most likely as the result of reduced osteoblasts synthetic activity in diabetes." (PMID 38598270, 2024). "Additionally, a reduced COL1A1 expression, observable in diabetes, correlates with decreased collagen synthesis." (PMID 39296334, 2024). "Diabetes was found to contribute to the development of tendinopathy through the downregulation of Scx, Mkx, Col1a1, Col1a2, and Bgn, and the upregulation of Col1a1, Scx, and Dcn contributed to the control of tendinopathy." (PMID 34737845, 2021). "A previous study showed that COL1A1 was expressed in type 2 diabetes mellitus, but this gene might be novel target for GDM." (PMID 33890634, 2021). "The observed alterations in the methylation levels of TERT and COL1A1 propound the hypothesis that diabetes potentially expedites the aging process, concomitantly impinging on the production of TERT and COL1A, ostensibly through the mechanism of promoter gene hypermethylation." (PMID 39296334, 2024). "Diabetes has been shown to increase the methylation of TERT in the kidney and COL1A1 in the skin, leading to reduced expression of these genes and expedited aging." (PMID 39296334, 2024). "To elucidate the impact of diabetes on gene expression in the kidney and skin, we examined the expressions of TERT and COL1A1." (PMID 39296334, 2024). "In this study, we elucidate the modulatory influence of diabetes on the aging process, focusing specifically on the modifications in TERT in the kidney and COL1A1 in the skin using mice of Swiss Webster strain as the diabetes model." (PMID 39296334, 2024).
diabetes (continued). "We further examined the expressions of several extracellular matrix(ECM) genes, COL1A1, COL4A1, and FN1, because the gene set enrichment analysis indicated enrichment of ECM deposition by MECs in diabetes." (PMID 39739865, 2024). "The suggested mechanism proposes that diabetes expedites aging processes through the hypermethylation of TERT and COL1A1 promoters." (PMID 39296334, 2024). "Our findings suggest that diabetes triggers enhanced methylation of the TERT and COL1A1 promoters." (PMID 39296334, 2024). "Based on existing evidence, miR-133a overexpression has prevented myocardial fibrotic event in both AngII-related hypertension and diabetes, even though the effector proteins were different in diabetes (fibronectin and COL4A1) and AngII-related hypertension (COL1A1)." (PMID 33569393, 2020). "Our findings reveal a marked impact of diabetes on the methylation statuses of TERT and COL1A1, characterized by an elevation in methylation levels within the periodic group (1st–6th week) and a simultaneous, progressive attenuation in the expression of TERT and COL1A1 genes." (PMID 39296334, 2024). "With regard to stress and fibrosis pathways, analysis of key genes related to these pathways was unchanged with either diabetes or genotype, including Nrf2, procollagen, and Col1a1, suggesting that LV fibrosis is not a key feature contributing to diastolic dysfunction in this model." (PMID 38054572, 2023). "The role of hsa-miR-503 in pathomechanism of diabetes complications depends on mitochondrial activity (DHFR), cell cycle control (CCNE2), cell protection (SOD2), podocyte migration (ANLN), inflammatory process (IL10, EFE2, VEGFA) and fibrosis (COL1A1), showing its contribution to CKD development." (PMID 36859746, 2023). "However, compared with nondiabetic mice subjected to renal IR, mice with early diabetes subjected to renal IR exhibited moderate Col1a1 and Col3a1 gene expression." (PMID 34561469, 2021). "Through endothelial-specific expression of miR9, levels of COL1A1 and FN1 were both significantly reduced in diabetes and restored to baseline non-diabetic." (PMID 39042659, 2024). "However, existing methodologies primarily focus on whole-genome methylation; the mechanisms of COL1A1 and TERT in diabetes-induced aging are not entirely understood." (PMID 39296334, 2024).